PPARG (peroxisome proliferator activated receptor gamma)
Diseases named in the same sentence as PPARG in open-access papers (continued):
Sharing a sentence is not in itself a finding about the gene and the disease.
lung carcinoma (continued). "A first evidenceof clinical efficacy of PPARγ agonists ascancer chemopreventives in lung cancer was recently published." (PMID 18779870, 2008). "It is critical to understand that cancer-protecting effects of PPARγ agonists in lung cancer can be PPARγ dependent but also PPARγ independent." (PMID 18779870, 2008). "TZDs inhibittumor formationin a variety of animal models, including colon and lung cancers, and PPARγ over-expressionprotects against tumor development in a mouse model of lung tumorigenesis." (PMID 18769553, 2008). "The combinationof PPARγ agonists with other chemopreventiveagents emerges as a challenging issue in lung cancer chemoprophylaxis." (PMID 18779870, 2008). "Inhuman lung cancer, decreased expression of PPARγ correlated with poor prognosis and well-differentiatedadenocarcinomas had more PPARγ expression than poorly differentiated varieties." (PMID 18528522, 2008). "In spite of intensive studyexamining the biological effects of PPARγ activation in lung cancer, much less is know regarding the directtargets of PPARγ." (PMID 18509496, 2008). "Totest the role of PPARγ in chemoprevention of lung cancer, we have developed transgenicmice overexpressing PPARγ under the control of the surfactant protein C promoter, whichtargets expression to the distal lung epithelium." (PMID 18509496, 2008). "Treatment of lung carcinoma cell lines with rosiglitazone decreased proliferation via PPARγ-dependent upregulation of PTEN and inhibition of Akt activity, and also via PPARγ-independent inhibition of the mTOR pathway." (PMID 19125181, 2008). "Nevertheless,the data available to date regarding PPARγ are promising and justify engaging in clinicalstudies to determine the true role of PPARγ ligands in lung cancer, while further work shouldbe performed to identify more selective and effective strategies." (PMID 18704200, 2008). "Activation of PPARγ represents a potential target for both the treatment and prevention of lung cancer." (PMID 18509496, 2008). "This article reviews the existing biological and mechanistic experiments focusing on the role of PPARγ in lung cancer, focusing specifically on nonsmall cell lung cancer." (PMID 18509496, 2008). "Thisreview focuses on PPARγ, its role in lung carcinogenesis, and the potential therapeutic roleof PPARγ agonists in lung cancer." (PMID 18704200, 2008). "The PPARγ effect on apoptosis is mediated by thegeneration of ROS, and knockdown of POX by siRNA markedly decreases or blocksthe effects of PPARγ on ROS formation and apoptosis incolorectal cancer cell or nonsmall cell lung cancer cell, respectively." (PMID 18670615, 2008). "PPARγ is upregulated in human lung cancer and activation of PPARγ inhibits lung cancer cell growth." (PMID 40303399, 2025). "PPARγ promotes apoptosis in lung cancer cells by influencing the key steps in the intrinsic and extrinsic apoptosis pathways, which increase the levels of pro-apoptotic proteins like Bax and Bad, while decreasing the levels of anti-apoptotic proteins such as Bcl-2 and Bcl-XL." (PMID 41304753, 2025). "Notably, PPARγ downregulates ALDHs to suppress lung cancer growth, as seen with arachidonic acid-induced PPARγ activation, which reduces ALDH3A1 and increases lipid peroxidation in A549 cells." (PMID 41304753, 2025). "However, recent clinical studies have also demonstrated potential therapeutic benefits of PPARγ agonists in lung cancer, further illustrating its complex, tissue-specific actions." (PMID 41476922, 2025). "The role of PPARγ activation in lung cancer immunity remains a controversial issue, which may correlate with the complexity of the immune microenvironment." (PMID 38397426, 2024). "The mechanism of PPARγ in lung cancer-related EMT is not yet fully understood." (PMID 38397426, 2024). "The results of in vitro experiments indicated that ROB may inhibit the proliferation and metastasis of lung cancer cells and activate the PPARγ signaling pathway, as well as induce cellular autophagy." (PMID 39450260, 2024).
lung carcinoma (continued). "Moreover, vascular endothelial growth factor (VEGF) was drastically downregulated through the PPARγ/NF-κB signaling pathway in human lung carcinoma 95D cells." (PMID 38397426, 2024). "PPARγ promotes apoptosis in lung cancer through dysregulating critical factors in these pathways." (PMID 38397426, 2024). "Notably, PPARγ has been reported to downregulate certain members of the ALDH family to function as a lung cancer inhibitor." (PMID 38397426, 2024). "Troglitazone-mediated PPARγ activation induced the phosphorylation of extracellular signal-regulated protein kinases 1 and 2 (ERK1/2) and subsequently caused apoptosis in NCI-H23 lung cancer cells via a mitochondrial pathway." (PMID 38397426, 2024). "In this review, we summarize the molecular mechanism underlying the action of PPARγ agonists and highlight the role of PPARγ activation in the complex regulatory network of lung cancer, aiming to provide a reference for developing novel therapeutic strategies for lung cancer." (PMID 38397426, 2024). "Notably, although TZDs have some side effects, they are the most potent PPARγ agonists and have been conducted to explore anti-lung cancer effects in clinical settings." (PMID 38397426, 2024). "In the case of lung cancer, PPARγ has antiproliferative and proapoptotic properties and may also inhibit the development of primary tumors." (PMID 38920636, 2024). "Clinical studies have demonstrated the key role of PPARG in tumorigenesis and development in various types of tumors, including BC, liver cancer, lung cancer, and neurological tumors, through the inhibition of cancer cell proliferation or the promotion of cancer cell apoptosis and autophagy." (PMID 37334066, 2023). "In addition, it was found that endogenous PPARγ was decreased well before lung tumor formation, indicating a role for the endogenous PPARγ molecular pathway in lung cancer development." (PMID 37190124, 2023). "However, in lung cancer cells, due to altered PPARγ functional domains and a shortage of ligands, PPARγ tends to accumulate in the cytoplasm instead of being activated." (PMID 37556076, 2023). "PPARγ is found in human lung cancer cell lines and its expression levels have been correlated with the differentiation status relevant to carcinogenesis and the OS rate in lung cancer patients." (PMID 37556076, 2023). "Results from the extensive research conducted on PPARs over the years have elucidated that PPAR expression is altered in lung cancer, especifically PPARγ that has been targeted using varieties of agonists and antagonists in order to treat different lung cancer cell lines in vitro and models in vivo." (PMID 35631448, 2022). "MAP2K4 inhibited lung cancer cell invasion through the repression of PPARγ." (PMID 35954274, 2022). "PPARγ, which has a crucial role in the development and/or advancement of lung cancer, might be a promising new therapeutic target." (PMID 35631448, 2022). "Consequently, PPARγ activation in macrophages has been shown to fuel lung cancer progression and metastasis, especially through increased arginase 1 and TGFβ1 expression." (PMID 35954274, 2022). "This shows that PPARγ may have an important role in lung cancer development, and that PPARγ agonists can be helpful therapeutic agents as a therapy for lung cancer." (PMID 35631448, 2022). "PPARγ agonist activation in orthotopic and spontaneous murine lung cancer models significantly increased metastasis formation through its upregulated expression in macrophages, which contributed to tumor progression and metastasis through increased arginase 1 expression." (PMID 35954274, 2022). "PPARγ expression was studied in the two lung cancer cell lines." (PMID 35631448, 2022). "The enhanced expression of slc10a2 triggered the expression of PPARγ, which ultimately caused an increase in PTEN expression and decrease in mTOR expression, implying that bexarotene decreases lung cancer cell survival through the slc10a2/PPARγ/PTEN/mTOR signaling pathway." (PMID 35631448, 2022).
lung carcinoma (continued). "miR-130b overexpression promotes the lung cancer cell progression by PPARγ/VEGF-A/BCL-2." (PMID 35756697, 2022). "As a result, PPARγ mRNA levels might be used as a prognostic indicator in lung cancer, and the measurement of PPARγ mRNA levels might be useful as a marker for PPARγ agonist therapy of lung cancer." (PMID 35631448, 2022). "Therefore, bavachinin has been directed against lung cancer cells proliferation, by targeting the PPARγ ROS-regulated signaling pathway." (PMID 34500594, 2021). "Four differentially expressed MMRGs (ACADL, ALDH18A1, CPT1B, and PPARG) established a logistic regression model, which could effectively diagnose lung cancer." (PMID 34970420, 2021). "Furthermore, in lung cancer cells, a tumor suppressive function of PPARγ was contributed metabolic reprogramming, an essential biochemical adaptation required for cancer viability that is considered to be a crucial emerging hallmark of cancer." (PMID 33716977, 2021). "Moreover, some PPARγ agonists inhibited the growth of human lung cancer cells through the induction of apoptosis." (PMID 31993929, 2020). "PPARγ, a pivotal nuclear receptor regulating cellular metabolic processes, is also expressed in various carcinomas including colorectal, breast, pancreatic, and lung cancers." (PMID 32054125, 2020). "Previous studies showed that PPAR-gamma (PPARG) ligands might serve as potential therapeutic agents for nonsmall cell lung cancer (NSCLC)." (PMID 32565768, 2020). "Furthermore, we provide in vivo evidence that the subcutaneous injection of apoptotic lung cancer cells decreases the number of visible lung metastases of the primary subcutaneous tumor via PPARγ/PTEN signaling." (PMID 30842627, 2019). "Decreased expression of PPARG and increased expression of PTGS2 (Prostaglandin Endoperoxide Synthase 2) has also been shown to be associated with the prognosis of lung cancer, treatment with PPARG agonists lead to a decrease in the levels of PTGS2 thus inhibiting the growth of NSCLC." (PMID 31263479, 2019). "Treatment of lung cancer cell lines with pioglitazone – an agonist of the nuclear receptor peroxisome proliferator activated receptor gamma – decreased the proliferation rates via increased FAO; which activated the tumour suppressor protein retinoblastoma to effect cell cycle arrest." (PMID 30092766, 2018). "Thus, the worse prognosis in NSCLC individuals is consistent with the idea that ALOX15B-derived 15(S)-HETE plays a protective role in the course of lung cancer either by activating PPARγ or by downregulating the expression of pro-angiogenic genes." (PMID 28704416, 2017). "Given that PPARγ activation evidently modulates lipid metabolism in lung cancer and generally known for inhibiting cancer cell proliferation, we wondered how the biochemical feature of the nuclear receptor would be mechanistically involved in the tumor suppressive function." (PMID 29137280, 2017). "Having demonstrated that sumoylation of liganded PPARγ increases intracellular lipid accumulation, we next wanted to know the expression profile of lipid metabolic genes in the HBECs and the same lung cancer panels upon TZD treatment under serum-supplemented or -depleted condition." (PMID 29137280, 2017). "The chemopreventive effects of PPARγ agonists in lung cancer have been reported by several studies." (PMID 28316613, 2017). "LXR and PPARG activation significantly decreased glutathione levels, highlighting a potential inhibitory effect on proliferation through increased oxidative stress, a finding that has been reported for PPARG in lung cancer cells." (PMID 27401066, 2016). "PPARγ, initially known as a key regulator of adipocyte differentiation and glucose and lipid homeostasis, has now demonstrated its involvement in the biology of lung cancer, as discussed in detail below, as well as in a wide variety of other cancers." (PMID 27698657, 2016).
lung carcinoma (continued). "Therefore, the ability of PPARγ agonists to suppress the development not only of primary tumors but also of metastases makes their therapeutic application in lung cancer promising." (PMID 27698657, 2016). "Thus, prodifferentiation, antiproliferative, and proapoptotic functions of PPARγ activation identify PPARγ agonists as attractive agents for lung cancer." (PMID 27698657, 2016). "Thus, these antitumorigenic influences on the tumor microenvironment, combined with its antiangiogenic effect, further support PPARγ agonists for the treatment of lung cancer." (PMID 27698657, 2016). "Collectively, this study demonstrates COX-2 induction and subsequent COX-2-dependent activation of PPARγ as a hitherto unknown mechanism by which lovastatin lactone induces human lung cancer cell death." (PMID 26863638, 2016). "Accumulating evidence demonstrates that PPARγ agonists/activation are antitumorigenic in most cases, hindering proliferation, growth, and progression and inducing differentiation and apoptosis in lung cancer." (PMID 27698657, 2016). "In addition to demonstrating their effectiveness as monotherapy for lung cancer, PPARγ agonists also show synergistic effects with standard chemotherapy and potentially prevent chemotherapeutic resistance." (PMID 27698657, 2016). "This allowed us to identify a key role of PPARγ in lung cancer pathogenesis." (PMID 26244663, 2015). "Together with the PPARγ inhibition of lung cancer proliferation as previously reported, this result suggests that PPARγ suppression of COX2 expression might be important in modulating oncogene-induced malignant transformation of HBECs into lung cancer." (PMID 26244663, 2015). "Given this information, dogs may serve as an excellent model of naturally occurring NSCLC to study the efficacy and tolerability of combination PPARγ agonists and platinum-based drugs for treatment of lung cancer." (PMID 26334880, 2015). "The role of PPARγ agonists as anticancer agents has been well characterized in treatment of colon, gastric, and lung cancer, whereas, PPARγ antagonists have been shown to induce potent antiproliferative effects in many hematopoietic and epithelial cancer cell lines." (PMID 23431460, 2013). "It is over-expressed in many types of cancer, including colon, stomach, breast, and lung cancer, suggesting that regulation of PPARγ might affect cancer pathogenesis." (PMID 23516550, 2013). "In murine models, PPARγ over-expression prevents lung cancer." (PMID 24216701, 2013). "Conversely, forced expression of PPARγ enhanced murine lung cancer cell invasion." (PMID 22934105, 2012). "Many studies indicate that activation of PPARγ in cancer cells leads to differentiation and induction of apoptosis, which has resulted in considerable excitement regarding the use of TZDs and PPARγ agonists for the prevention and treatment of lung cancer." (PMID 22934105, 2012). "Tumor-promoting effects of PPARγ and PPARγ agonists need further investigation, and the effects of PPARγ activation on lung cancer cells may vary depending on tumor type or stage." (PMID 22934105, 2012). "The studies reviewed above implicate PPARγ in lung cancer cell biology." (PMID 22934105, 2012). "Collectively, these studies suggest that targeting PPARγ may have important chemopreventive applications for lung cancer." (PMID 22145026, 2011). "Overexpressing PPARγ in nonsmall cell lung cancer cells inhibited tumor number and metastasis." (PMID 20182546, 2010). "PPARγ affects inflammatorygene expression, cell division, apoptosis, invasion, release of proangiogeniccytokines, and differentiation in many cancer types including lung cancer." (PMID 18769553, 2008). "Epithelial mesenchymaltransition has been associated with cancer progression and metastasis.While this is still somewhat of a controversial area, activation of PPARγ in lung cancer cells appears to inhibit invasiveness, at least inpart through inhibiting or reversing EMT." (PMID 18509496, 2008).